YY1 (YY1 transcription factor)
Diseases named in the same sentence as YY1 in open-access papers (continued):
Sharing a sentence is not in itself a finding about the gene and the disease.
infection (25 papers, 2008 to 2025). The state of being infected such as from the introduction of a foreign agent such as serum, vaccine, antigenic substance or organism. "Given that YY1 deficiency results in decreased expression of IFN-β after poly(I:C) treatment or infection with SeV, we hypothesized that this effect would also occur during PRRSV infection and, thus, facilitate viral replication." (PMID 38953350, 2024). "Together, the quantitative proteomic analysis of YY1 knockdown cells revealed that a large number of YY1 sensitive proteins are related to infection and immunity based on published reports." (PMID 40373059, 2025). "Upon hrHPV infection, the increased YY1-due to reduced miR-29a expression and enhanced recruitment by HPV E7 (bottom)-outcompetes TFAP2 for binding at the promoter core region and transactivates the lnc-FANCI-2 promoter." (PMID 40953061, 2025). "Inhibition of nuclear transport by leptomycin B attenuates infection-mediated YY1 redistribution and reduces Leishmania survival." (PMID 40373059, 2025). "Together, this review will add a novel function to the growing list of roles assigned to YY1 and unveil its importance in the field of infection and immunity." (PMID 40801584, 2025). "Nevertheless, proteomic data presented here can be a valuable resource for other researchers interested in YY1 functions and its role in infection and immunity." (PMID 40373059, 2025). "For this investigation, they employed siRNA-mediated downregulation of macrophage YY1 for 24 h before infection." (PMID 40801584, 2025). "This suggests that Leishmania induces YY1 translocation to the cytoplasm from the nucleus during infection." (PMID 40373059, 2025). "Strikingly, Leishmania redirects YY1 from its primary location of the nucleus to the cytoplasm during infection." (PMID 40373059, 2025). "The PRRSV nucleocapsid (N) protein was used as an infection indicator, and the protein level of YY1 increased with PRRSV infection in vitro." (PMID 38953350, 2024). "The infection with LV-sh-YY1 contributed to improved lung pathological manifestations in the bleomycin model mice, while LV-sh-THY1 treatment worsened the lung pathological manifestations, which were alleviated by LV-sh-YY1 (P < 0.05)." (PMID 32396525, 2020). "Data of Western blot analysis showed that YY1 levels down-regulated by infection with miR-34a- or miR-34bc-expressing adenoviruses were restored after transfection with miR-34 family-insensitive YY1-expressing construct in SC-M1 cells." (PMID 24970812, 2014). "Interestingly, proteins that are upregulated by YY1 knockdown are more involved in infection and immunity." (PMID 40373059, 2025). "It was also observed that Leishmania redirected nuclear YY1 to the cytoplasm during infection." (PMID 40373059, 2025). "In addition to characterizing the infection-related macrophage proteome, this study revealed that approximately 5% of the identified proteins are sensitive to the abundance of YY1." (PMID 40801584, 2025). "During infection, Leishmania modulates several host macrophage proteins, employing YY1, which may be to its advantage." (PMID 40801584, 2025). "YY1 controls the expression and interacts with a large subset of genes involved in basic metabolic pathways, protein synthesis, and, surprisingly, some viral genomic elements at different stages of infection." (PMID 35408813, 2022). "Our research indicated that the GAS5/YY1/STX17 pathway may represent a new regulatory network that controls the disruption of autophagy in response to infection by Acinetobacter baumannii." (PMID 34304694, 2021). "Moreover, the functions and mechanisms involving cross-talk between GAS5 and YY1 in the induction of autophagy by infection with Acinetobacter baumannii have yet to be elucidated." (PMID 34304694, 2021). "Finally, we detected the effect of Acinetobacter baumannii on the expression of YY1 by western blotting and found that the expression of YY1 gradually decreased with the extension of infection time." (PMID 34304694, 2021).
infection (continued). "Similarly, Ad‐FAM3C infection also up‐regulated the expression levels of YY1 and HSF1 mRNAs and proteins with Akt activation when compared with Ad‐GFP–treated cells." (PMID 30887707, 2019). "Infection with the YY1 knockdown construct resulted in a 50% reduction in cell-surface PSCA levels following R1881 stimulation compared with vector infected Pten CaP8 cells, while YY1 knockdown abrogated the increase in cell-surface PSCA levels in Pten CaP2 cells." (PMID 22536409, 2012). "Notably, proteins upregulated by YY1 knockdown are more involved in infection and immunity." (PMID 40801584, 2025). "The list of transcription factors modulated by the infection includes the IRF, MYC-MAX, NFY, and E2F families; RELA; YY1; CREB1; and others." (PMID 37998351, 2023). "The YY1-mediated positive regulation of viral transcription has been also reported for the HLJ1 (heat shock protein) of HBV, especially at an early stage of infection." (PMID 35408813, 2022). "At these early times after infection, NSs colocalized perfectly with SAP30 whereas colocalization with YY1 appeared only partial." (PMID 18225953, 2008). "Expression of YY1 over 48 hours of infection at both MOIs was not significantly affected relative to non-infected control cells." (PMID 40373059, 2025). "Furthermore, YY1 and FASN protein levels in the livers of NAFLD mice were further increased after LV-miR-192-5p inhibitor infection." (PMID 38254634, 2023). "Consequently, siRNA-mediated depletion of YY1 or PRMT5 rescued ITCH expression, thereby compromising the levels of Mtb-induced ADRP and CD36 and limiting FM formation during infection." (PMID 35658060, 2022). "Infection using an empty vector control resulted in predominantly Type III and IV Xist RNA patterns, with very few Type I/II cells (~3–5%; for 3 independent experiments), similar to our previous observations for YY1 deletion in splenic B cells." (PMID 28991910, 2017). "YY1 and Rbpj/CBF-1 may have dual roles, both in repression of ie expression in latency and in activating ie gene expression for productive infection." (PMID 23698401, 2013). "There was no significant change in human PSCA message levels in LNCaP cells, despite nearly 100% infection of the cells (not shown) and efficient knock down of YY1 protein." (PMID 22536409, 2012). "Both Pten CaP2 and Pten CaP8 cells die 96 hours following YY1siRNA infection (data not shown) suggesting that YY1 knockdown adversely affects viability of these cells." (PMID 22536409, 2012). "Given the criteria above and the fact that YY1 could target TLR7 and TLR9 signaling, type I and II interferon production/pathways, reported as effective for virus clearance during infection, if activated, establishes YY1 as the best TF with the best potential as a drug target for BCoV therapy." (PMID 32872640, 2020). "Therefore, the inability of YY1 to bind to its −122 site after ZH infection cannot be assigned to a general lack of accessibility of the promoter region." (PMID 18225953, 2008). "Repression of the cell cycle regulator p27 was recently shown to require binding of YAP alongside the transcriptional repressors YY1 and EZH2; YAP-mediated recruitment of transcriptional repressors may similarly drive the reduced expression of certain YAP target genes during infection." (PMID 36923592, 2023).
neurodevelopmental disorder (11 papers, 2020 to 2025). A behavioral and cognitive disorder with onset during the developmental period that involves impaired or aberrant development of intellectual, motor, or social functions. "YY1 malfunction causes serious consequences: YY1−/− genotype causes peri-implantational lethality in mice and YY1+/− results in neurodevelopmental disorder in humans." (PMID 37686614, 2023). "YY1 encodes another transcription factor with a recognized and established role in myelination; pathogenic variants in YY1 cause a severe neurodevelopmental disorder as well as early-onset dystonia." (PMID 38835919, 2022). "Human patients with Yy1 haploinsufficient mutations display neurodevelopmental disorders." (PMID 32703236, 2020). "A previous study has shown that transcription factor YY1 binds to the promoter region of the Stx1a gene related to synaptic transmission and neurodevelopmental disorders and negatively regulates its transcription in a cell/tissue-specific manner." (PMID 35433684, 2022). "Several studies show that YY1 plays a role in neurodevelopmental disorders, but the mechanisms behind this are still incompletely understood." (PMID 33102493, 2020). "We demonstrate that FBRSL1 associates with the transcription factor Yin Yang 1 (YY1) and binds upstream of Bromodomain And PHD Finger containing 1 (BRPF1) and Lysine Acetyltransferase 6 A (KAT6A), two epigenetic regulators involved in embryonic development and linked to neurodevelopmental disorders." (PMID 40658195, 2025). "Herein, we describe four patients with rare neurodevelopmental disorders (SON, ZMYND11, DNMT1 and YY1-related diseases), who received a genetic assignment only in the adulthood." (PMID 35172867, 2022).
hematological malignancies (7 papers, 2016 to 2025). "YY1 knockdown reduced cell proliferation of HL-60-sh-YY1-doxy and OCI-AML3-siYY1 cells; in addition, several studies have shown that YY1 upregulation inhibits apoptosis and favors growth and cell proliferation in both solid tumors and hematological malignancies." (PMID 37568827, 2023). "Neither YY1 ablation nor ectopic expression was associated with the emergence of hematological malignancies; however, YY1 overexpression increased the myeloid lineage." (PMID 33728560, 2021). "Prevalently, in hematological malignancies the role of YY1 seems to be pro-tumorigenic." (PMID 32899428, 2020). "When dysregulated, YY1 may be linked with lymphomagenesis and several reports describe YY1 as negative prognostic marker in the vast majority of hematological malignancies." (PMID 32899428, 2020).
metabolic disorders (6 papers, 2018 to 2025). "Modulating the activity of RKIP and YY1 represents a promising therapeutic strategy for the treatment of metabolic diseases." (PMID 41459495, 2025). "This review synthesizes current insights into the molecular structures, signaling pathways, and tissue-specific functions of RKIP and YY1, emphasizing their interplay in shaping immune responses in metabolic disorders." (PMID 41459495, 2025). "In contrast, Hep_Ass1 exhibited high expression of the transcription factor Yy1 which is deeply involved in metabolic disorders, indicative of its role in metabolism." (PMID 37808269, 2023). "Conversely, inhibiting YY1 activity could suppress the transcription of pro-inflammatory genes, thereby mitigating the chronic inflammation characteristic of metabolic disorders." (PMID 41459495, 2025). "Two subsets with distinct differentiation states, involving 40 hub CDRGs regulated by YY1 and EGR2, were identified by single-cell RNA sequencing data, of which subset I was related to hypoxia, metabolic disorders, and inflammation, and subset II was associated with immune responses and ferroptosis." (PMID 34966734, 2021). "Also, compared with that in the ox-LDL + shRNA-NC group, when YY1 was downregulated, ox-LDL-mediated cholesterol metabolism disorders were alleviated, with CE/TC below 50%." (PMID 36330745, 2022).
neurodegenerative disease (6 papers, 2014 to 2023). A disorder of the central nervous system characterized by gradual and progressive loss of neural tissue and neurologic function. "YY1 is a ubiquitous transcription factor previously noted to regulate several genes associated with neurodegenerative diseases including BACE1 and APP, SNCA, EAAT2, MTOR and PPARGC1A." (PMID 25187168, 2014). "Yin Yang 1 (YY1) is implicated in neurodegenerative diseases." (PMID 31671574, 2019). "In multiple neurodegenerative diseases, YY1 function is degraded through distinct mechanisms, including protein utilization, protein degradation, and ectopic nuclear/cytoplasmic shuttle (N/C)." (PMID 36970516, 2023). "A future goal in YY1 research is to discover other potential mechanisms that lead to YY1 dysfunction in neurodegenerative diseases, such as ectopic changes after translation." (PMID 36970516, 2023). "In neurodevelopmental and neurodegenerative disease, the crucial role of YY1 in cellular processes in the central nervous system is further underscored." (PMID 33102493, 2020). "Moreover, YY1 was also found to be reduced in the brains of patients with other neurodegenerative disease." (PMID 37044212, 2023). "It would be tempting to speculate that the protective function requires tightly regulated levels of YY1, while aberrant levels contribute to the onset and progression of neurodegenerative diseases." (PMID 33102493, 2020).
adenocarcinoma (4 papers, 2020 to 2023). A common cancer characterized by the presence of malignant glandular cells. "The results of the current study suggest that ADT upregulates the level of YY1 expression, is involved in PCa cell plasticity, and mediates trans‐differentiation from adenocarcinoma to NE carcinoma via transcriptional activation of FZD8." (PMID 37771187, 2023). "When the single cells were analyzed and pooled based on their adenocarcinoma stage, interestingly both Yy1 and Rkip genes increased in their expression, and Rkip was expressed in a higher percentage of cells compared to Yy1." (PMID 35205667, 2022). "Furthermore, our examination of the TCGA database demonstrated a positive association between YY1 and HDAC2 expression in both lung and adenocarcinoma tissues." (PMID 37495623, 2023).
psychiatric disorder (4 papers, 2020 to 2024). A disorder characterized by behavioral and/or psychological abnormalities, often accompanied by physical symptoms. "Twelve known ASD SNPs are associated with validated TF binding sites of YY1, E2F1 and USF2 enriched in neurodevelopmental and neuro-psychiatric disorder PPI network." (PMID 33080834, 2020).
cardiovascular diseases (3 papers, 2019 to 2022). "It is now of great interest to know whether this reactivation of cardiac cell cycle is a common mechanism for sarcomere deficiency and enhancing of this process by Yy1 or other regulators is able to suppress cardiovascular disease related to sarcomere." (PMID 31705051, 2019). "Studies have confirmed that YY1 was abundant in cardiomyocytes and was differentially expressed in many cardiovascular diseases, including CHD." (PMID 35692080, 2022).
kidney disease (2 papers, 2023 to 2024). "Previously, the role of YY1 in the development of renal lesions in different kidney diseases has been illustrated, although the mechanism differed." (PMID 37507403, 2023).
lung (2 papers, 2020 to 2023). "Another study revealed that Yin Yang-1(YY1), a multifunctional transcription factor, bound to the promoter region of PVT1 and motivated its transcription through the consensus YY1 motif to promote cell proliferation, migration and invasion in lung cancer." (PMID 31897242, 2020).
retinopathies (2 papers, 2023 to 2025). "Targeting the lactate/p300/YY1 lactylation/FGF2 axis may provide new therapeutic targets for proliferative retinopathies." (PMID 37085894, 2023).
neurological diseases (1 paper, 2020). "Recent research has revealed that YY1 plays a critical role in neural development, neuronal function, developmental myelination, and neurological diseases." (PMID 32206061, 2020).
peripheral neuropathy (1 paper, 2025). A disorder affecting the peripheral nervous system. "Changes in expression levels of YY1 are associated with different forms of peripheral neuropathy." (PMID 40343270, 2025).
YY1 also shares sentences with these, for which no sentence is quoted: Ataxia (3 papers); dilated cardiomyopathy (3); fibrosis (3); Sepsis (3); uterine cancer (3); endometrial stromal sarcomas (2); hepatoblastoma (2); lymph node metastasis (2); metabolic dysfunction-associated steatotic liver disease (2); metastatic melanoma (2); uterine corpus endometrial carcinoma (2); acute kidney injury (1); acute leukemia (1); adenoma (1); adrenocortical carcinoma (1); adult T-cell leukemia (1); AIDS (1); alopecia areata (1); anxiety disorder (1); astrocytoma (1); atrial fibrillation (1); Atrophy (1); bacterial infection (1); blastoma (1); brain cancer (1); brain disorder (1); cancers of the digestive system (1); cardiomyopathy (1); cervical intraepithelial neoplasia (1); cervix (1).
A further 68 diseases each share a sentence with YY1 in 1 paper.